USP37 (ubiquitin specific peptidase 37)
Diseases named in the same sentence as USP37 in open-access papers (continued):
Sharing a sentence is not in itself a finding about the gene and the disease.
tumor (continued). "Additionally, ESR1, OTUD6B, USP2, and USP37 showed a positive correlation with risk scores, while USP22 exhibited a significant negative correlation with risk scores (r = -0.7, p < 0.0001), suggesting a potential role for these genes in ESCC tumor progression and patient prognosis." (PMID 39742278, 2024). "We also analyzed the xenografts tumour tissues and found that the BLM level is higher in the USP37 WT tumors compare with USP37 S114A tumors." (PMID 34606619, 2021). "Further experiment results showed that the downregulation of USP37 increased the sensitivity of MCF-7/ADR cells to adriamycin in vitro and inhibited the tumor growth of MCF-7/ADR cells in vivo." (PMID 33390801, 2021). "USP37 KD in MCF7 cells also increased sensitivity to chemotherapeutic agents such as cisplatin by decreasing the BCL2/BAX ratio and attenuating tumor growth in vivo." (PMID 34758854, 2021). "Consequently, USP37 is not a bona fide oncogene or tumor suppressor though its oncogenic functions are predominantly signified by various studies." (PMID 34758854, 2021).
infection (2 papers, 2018 to 2025). The state of being infected such as from the introduction of a foreign agent such as serum, vaccine, antigenic substance or organism. "We knocked down USP37 in MCF-7 and MDA-MB-231 cells via infection with lentivirus expressing USP37#2 shRNA or control lentivirus (shScramble); we confirmed USP37 gene expression by examining protein levels." (PMID 30482232, 2018). "To investigate how USP37 affects the function of SAMHD1, we knocked down or overexpressed USP37 in THP-1 cells, the target cells for SIV infection, and examined its impact on the infection of SIVmac239 WT or SIVmac239 ΔVpx." (PMID 39655951, 2025). "Accordingly, the infectivity of SIVmac239-WT-GFP was found to be significantly increased in the USP37 knockdown group, indicating that USP37-knockdown led to more unstable SAMHD1 upon SIVmac239 infection." (PMID 39655951, 2025).
USP37 also shares sentences with these, for which no sentence is quoted: adenocarcinoma (1 paper); Clear cell renal cell carcinoma (1); kidney chromophobe (1); leukemia (1); metabolic disease (1); Obesity (1); prostate adenocarcinoma (1); prostate carcinoma (1); renal adenocarcinoma (1); sarcoma (1); Stroke (1).